MELK (maternal embryonic leucine zipper kinase)
Diseases named in the same sentence as MELK in open-access papers (continued):
Sharing a sentence is not in itself a finding about the gene and the disease.
glioma (continued). "Consistent with the CGGA and TCGA analyses, the immunohistochemistry assay also revealed that a high level of MELK was associated with older age, increased WHO grade, IDH wild type, and 1p19q non-codeletion molecular subtypes, all of which represent higher malignancy of glioma." (PMID 36353126, 2022). "In addition, a study about high-grade gliomas showed that MELK could inhibit radiation-induced apoptosis in glioma stem cells." (PMID 32391256, 2020). "The MELK/FOXM1 axis has received more attention in recent years due to its significance in high-grade gliomas, and newer investigations have uncovered other upstream regulators involved in chromatin remodeling, such as SAT1 in the regulation of MELK and EZH2." (PMID 37821870, 2023). "Along with the increase in the glioma grade (WHO classification), the expression level of MELK was significantly increased in the order of grades II, III, and IV." (PMID 36353126, 2022). "However, the function role of MELK in the microenvironment of glioma is still largely unknown." (PMID 36353126, 2022). "The results showed that significant positive correlations existed between MELK expression and B7-H3, CTLA4, LAG3, PD-1, PD-L1, and TIM3 expression in glioma." (PMID 36353126, 2022). "When MELK is upregulated in GBM, EphB2 will be upregulated and promote EMT and glioma stem cell (GSC) maintenance." (PMID 36338770, 2022). "The expression profiles of MELK, EZH2 and NF-κB represent another prognostic factor for glioma patients, further supporting the clinical application in precise diagnosis and treatment." (PMID 31380279, 2019). "Conversely, patients with low levels of MELK/EZH2/NF-κB and low-grade gliomas had increased survival." (PMID 31380279, 2019). "Oncogenic roles of maternal embryonic leucine-zipper kinase (MELK) and enhancer of zeste homolog 2 (EZH2) have been reported to play a crucial role in glioma tumorigenesis." (PMID 31380279, 2019). "In glioma stem-like cell (GSC), maternal embryonic leucine-zipper kinase (MELK) increases the activity of FOXM1 by interaction with its N-terminus and promoting its phosphorylation by Plk1." (PMID 30208972, 2018). "Expression of MELK and STMN1 was knocked out by specific siRNA transfection of U87MG glioma cell line." (PMID 26973435, 2016). "As before we confirmed that mNS GSC have a higher expression level of the stem cell markers CXCR4, MELK, PTCH, CD44, CD133, MSl1 and CD90, while GL261 GDC expressed higher level of the differentiated glioma marker glial fibrillary acidic protein (GFAP)." (PMID 27073883, 2016). "In GBM and other High Grade Gliomas (HGG), experimental radiation treatment strongly upregulated MELK in vitro and in vivo." (PMID 25852826, 2015). "Using 24 grade III glioma samples and 56 GBM samples, we found that FOXM1 RNA expression in individual tumors was correlated with MELK expression (p < .001)." (PMID 23404835, 2013). "Interestingly, MELK mediates EZH2 phosphorylation to promote the progression of human cancers, such as glioma." (PMID 38652219, 2024). "We examined MELK, EZH2, and NF-κB expression by immunohistochemistry and demonstrated that MELK, EZH2, and NF-κB were abundantly enriched in the nuclei of high-grade gliomas with the average score ranking from 1.2 to 1.8, compared with the low-grade and normal adjacent tissues." (PMID 31380279, 2019). "Given that exaggerated profiles of the MELK/EZH2/NF-κB axis are being identified in tissues with a high percentage of Ki-67+, such as the embryonic subventricular zone (SVZ) and in high-grade gliomas, it seems likely that these proteins function to promote proliferation." (PMID 31380279, 2019). "In addition to assessing the role of MELK/EZH2/NF-κB axis in different histopathological gliomas, additional studies will investigate their function in genetic subgroups of glioma." (PMID 31380279, 2019).
glioma (continued). "Interestingly, MELK activity together with FOXM1 has been shown to positively regulate both SOX2 and EZH2 in other tumours, such as glioma and medulloblastoma." (PMID 29437778, 2018). "In glioma tissues of GBM, mesenchymal subtype cells have the high expression of mesenchymal subtype signature genes, including chitinase 3 like 1 (CHI3L1), collagen type V alpha 1 chain (COL5A1), fibronectin 1 (FN1), cyclin B1 (CCNB1), and maternal embryonic leucine zipper kinase (MELK)." (PMID 35158782, 2022). "Specifically speaking, the stemness-related regulators, CD133, MELK and SOX2 were substantially downregulated following transfection of shCDC42EP3-harboring lentivirus into SHG-44 cells, indicating concurrent reduction in expression of CDC42EP3 and stemness of glioma stem cells." (PMID 35365622, 2022). "In glioma, FOXM1 interacts with critical signaling pathways and molecules, including MELK, STAT proteins, Wnt/β-Catenin, growth factors, and non-coding RNAs." (PMID 37821870, 2023). "As for the molecular type, the expression of MELK was obviously lower in the IDH mutant and 1p19q codeletion gliomas than in the IDH wild type and 1p19q non-codeletion ones." (PMID 36353126, 2022). "To verify the role of phosphorylated EZH2 in glioma progression, we examined H3K27-methylation in GSCs in the presence or absence of lentivirus carrying shRNA against MELK or pharmacological inhibitors." (PMID 31380279, 2019).
prostate carcinoma (29 papers, 2010 to 2026). A carcinoma that arises from epithelial cells of the prostate gland. "Taken together, these results confirmed that MELK protein was indeed overexpressed in prostate cancer, and suggested that cytoplasmic MELK was associated with tumour progression." (PMID 29437778, 2018). "Taken together, these results strongly suggest that MELK promotes the survival of prostate cancer cells and the expression of genes associated with tumour progression." (PMID 29437778, 2018). "We found that MELK expression was required for cell survival, affected the expression of genes associated with prostate cancer progression and was associated with biochemical recurrence." (PMID 29437778, 2018). "Actually, MELK seems to be a druggable target as MELK overexpression has also been associated with poor prognosis in breast and prostate cancer." (PMID 26973435, 2016). "Moreover, MELK has been shown to be associated with poor prognosis in breast and prostate cancer patients." (PMID 26973435, 2016). "In prostate cancer cells, a decrease in its expression promotes the expression of proliferation-related genes MELK, NCAPG, BUB1, and CDK1, thereby promoting cell proliferation." (PMID 41546098, 2026). "A recent study suggested that an immunosuppressive drug cyclosporin A inhibits E2F8 transcription factor via MELK in prostate cancer." (PMID 38605607, 2024). "SOX11, CRISP3, KIF18B, and MELK expression levels have also been found to be positively correlated with poor prostate cancer patient prognostic outcomes, while ZNF556 has been associated with poor colon cancer patient prognosis." (PMID 36245556, 2022). "BUB1B accelerates the progression of prostate cancer via the transcriptional modulation of MELK, which can be used as a clinical prognostic factor and drug target for prostate cancer." (PMID 34838000, 2021). "For example, BUB1B accelerates prostate carcinoma proliferation through transcriptionally modulating MELK." (PMID 34987580, 2021). "MELK is involved in cancer cell survival and invasiveness and has been already suggested as a novel potential therapeutic target in prostate cancer." (PMID 33672425, 2021). "Recent studies indicated that MELK was highly expressed in several human cancers, including breast, prostate cancer, gastric cancer, and lung cancer." (PMID 34350110, 2021). "BUB1B was identified as an oncogene in prostate cancer through BUB1B‐dependent regulation of MELK transcription." (PMID 32977361, 2020). "Using this approach, we have identified maternal embryonic leucine zipper kinase (MELK) as a potential therapeutic target in prostate cancer." (PMID 29437778, 2018). "Our data suggest that inhibition of MELK has the potential to be an effective therapeutic strategy in prostate cancer." (PMID 29437778, 2018). "Recently, TOP2A, MELK, and CENPF were also reported to be putative targets of miR-27a-5p and have been implicated in prostate cancer progression." (PMID 29415999, 2018). "Using this approach, we revealed a functional role for the kinase MELK as a driver and potential therapeutic target in prostate cancer." (PMID 29437778, 2018). "We validated one of these potential therapeutic targets, the protein kinase MELK, by showing that silencing of this gene inhibits prostate cancer cell proliferation and induces cell death in vitro." (PMID 29437778, 2018). "To further validate the anti‐apoptotic role of MELK in prostate cancer, we treated C4‐2b cells with OTS167 in vitro and assessed the rate of apoptosis using Annexin V staining." (PMID 29437778, 2018). "In prostate cancers with high Gleason scores, MELK expression was elevated and its inhibition by RNAi detailed putative functions in chromatin modification, embryonic development, and cell migration." (PMID 24885567, 2014). "PLK1 and MELK have been suggested to be potential targets in prostate cancer." (PMID 33632199, 2021). "MELK is upregulated in prostate cancer and related to aggressiveness." (PMID 33632199, 2021).
prostate carcinoma (continued). "We have then validated the functional importance of MELK for tumour growth both in vitro and in vivo and identified a new mechanism through which this kinase may drive proliferation and viability of prostate cancer cells." (PMID 29437778, 2018). "Notably, there was a statistically significant correlation between MELK expression and sensitivity to OTS167, supporting the notion that the effects of OTS167 on prostate cancer cell viability are at least partially mediated through MELK." (PMID 29437778, 2018). "We then set out to investigate the effects of MELK abrogation on prostate cancer cells in vitro." (PMID 29437778, 2018). "Inhibition of one of these potential targets, the kinase MELK, might be a promising strategy for treatment of prostate cancer." (PMID 29437778, 2018). "Expression of MELK has been reported in canine prostate carcinoma derived cell lines." (PMID 30517191, 2018). "Treatment with a compound that inhibits MELK strongly reduced prostate cancer growth in vivo." (PMID 29437778, 2018). "We confirm alterations in six genes previously associated with prostate cancer (MAP3K7, MELK, RCBTB2, ELAC2, TPD52, ZBTB4), and also identify 94 genes not previously linked to prostate cancer progression that would not have been detected using either transcript or copy number data alone." (PMID 26501111, 2015). "Furthermore, in vitro silencing of MELK can weaken the proliferation of prostate cancer cells, and in vivo tests also proved that an inhibitor of MELK could repress the growth of prostate cancer." (PMID 33632199, 2021). "Therefore, due to its emerging role as a potential therapeutic target in multiple cancers, as well as the recent development of a small‐molecule MELK inhibitor, we selected this kinase for further study in order to determine its value as a potential therapeutic target in prostate cancer." (PMID 29437778, 2018). "In prostate cancer, BUB1B was found to accelerate cell proliferation by transcriptionally regulating MELK." (PMID 41163302, 2025). "Based on our cross‐species data, we would thus predict a compound such as OTS167, which is able to inhibit both MELK and BUB1, to be more effective in targeting prostate cancer cells than single inhibitors of either kinase." (PMID 29437778, 2018). "Our previous studies revealed that tumor-suppressive miR-145-3p was closely involved in human cancer pathogenesis by targeting oncogenes, for example, MTDH in LUSQ; MELK, NCAPG, BUB1, and CDK1 in prostate cancer; MYO1B in head and neck cancer; and MYO1B and DHRS2 in esophageal cancer." (PMID 31514295, 2019). "Having demonstrated that silencing of MELK and treatment with OTS167 greatly reduced prostate cancer cell proliferation and viability in vitro, we aimed to evaluate whether targeting this kinase might be a promising strategy to reduce tumour growth in vivo." (PMID 29437778, 2018). "Therefore, treatment with MELK inhibitor could be a desirable anticancer strategy for tumors with enhanced activity in the PI3K/Akt/mTOR pathway, such as breast, lung, ovarian, and prostate cancers." (PMID 26871945, 2016).
hepatocellular carcinoma (18 papers, 2013 to 2026). A malignant tumor that arises from hepatocytes. "The molecular mechanism flowchart showed that MELK stabilizes FABP5 to amplify the anti-hepatoma cancer effect of RFA." (PMID 39871325, 2025). "Using ELISA, we also found that MELK knockdown reduced FABP5 secretion by hepatoma cells with CHX exposure time." (PMID 39871325, 2025). "Both in vivo and in vitro experiments suggested that MELK knockdown inhibited hepatoma cell growth, invasion, stemness, and tumorigenesis by inducing apoptosis and ICD." (PMID 39871325, 2025). "Using a subcutaneous tumor formation model in nude mice, we observed that miR-21-5p inhibits the ferroptosis of hepatoma cells by regulating the AKT/mTOR signaling pathway through MELK in vivo." (PMID 37008632, 2023). "MiR-214-3p inhibits cell proliferation and cell cycle distribution via targeting MELK in hepatocellular carcinoma." (PMID 32808668, 2020). "In small cell lung cancer and hepatocellular carcinoma, MELK expression is consistently elevated in cancer relative to normal tissues." (PMID 31412643, 2019). "Additionally, MELK knockdown in hepatoma cells appeared to induce hepatoma cell apoptosis and ICD, leading to inhibition of cell viability." (PMID 39871325, 2025). "MELK regulated the AKT/mTOR signaling pathway, causing changes in the levels of GPX4, GSH, FTH1, xCT, heme oxygenase 1(HO-1), reactive oxygen species, and Fe2+ to regulate the ferroptosis of hepatoma cells." (PMID 37008632, 2023). "MELK is an oncogenic kinase essential for early recurrence of hepatocellular carcinoma." (PMID 31788359, 2019). "Therefore, we hypothesized that MELK promotes PI3K/Akt/mTOR signaling by enhancing the protein stability of FABP5 in hepatoma cells." (PMID 39871325, 2025). "The findings demonstrated that MELK stimulated the expression of DLAT in hepatocellular carcinoma (HCC) cells through the activation of the PI3K/mTOR signaling pathway." (PMID 37949877, 2023). "In contrast, knockdown of MELK significantly suppressed tumor cell proliferation, colony formation, stemness, and tumorigenicity, and induced apoptosis, mitosis, and DNA damage both in vitro and in nude mice models in gastric cancer, hepatocellular carcinoma and cervical cancer." (PMID 32047721, 2020). "When we overexpressed Ub molecules in hepatoma SK-HEP1 and HCC-LM3 cells, Ub molecules were more highly expressed in MELK knockdown cells." (PMID 39871325, 2025). "In hepatocellular carcinoma (HCC), recent studies have highlighted MELK’s potential oncogenic role." (PMID 40564876, 2025). "In addition, we generated MELK knockout and FABP5 knockout hepatoma cell lines for in-depth investigation." (PMID 39871325, 2025). "Besides, heat-up or MELK knockdown inhibited cell viability, exhibiting high expression of Eth-1 and low expression of Cal-AM, and also inhibited proliferation, showing low detection of EDU staining, and combined treatment enlarged those effects in hepatoma cell lines." (PMID 39871325, 2025).
melanoma (17 papers, 2007 to 2025). A malignant, usually aggressive tumor composed of atypical, neoplastic melanocytes. "The Maternal Embryonic Leucine Zipper Kinase (MELK) has been implicated as a cancer dependency and putative drug target in multiple cancer types, including melanoma, colorectal cancer, and triple-negative breast cancer." (PMID 29417930, 2018). "This suggests that rs60970102 may impact alternative splicing patterns of MELK, providing a putative biological mechanism by which the observed genetic association in MELK may affect melanoma progression." (PMID 36741706, 2022). "As such, the prior correlative and causative evidence supporting MELK as a novel therapeutic target in melanoma, along with the suggestive genetic association data from this study, provide further indications in support of a focused investigation of MELK and its role in melanoma progression." (PMID 36741706, 2022). "Moreover, MELK is important in melanoma progression and therefore may be implicated in resistance against current therapies." (PMID 33431809, 2021). "MELK is known to be overexpressed in multiple types of cancer, including breast cancer, melanoma, and renal cell carcinoma." (PMID 37175795, 2023). "Our study provides suggestive evidence of novel melanoma germline prognostic markers, implicating two candidate genes: an oncogene MELK and a tumor suppressor SH3BP4, both previously suggested to affect CM progression." (PMID 36741706, 2022). "A bio-informatic analysis of expression data on melanoma shows that MELK is significantly overexpressed in metastatic melanoma compared to primary melanoma." (PMID 33431809, 2021). "Noticeably, knocking-down AMPK using siRNA or over-expressing MELK using adenoviral construct partially restored cell viability and the combination of both almost completely abolished the anti-melanoma effect of CRO15." (PMID 33431809, 2021). "In a previous study, MELK has been proven to promote melanoma growth by activating NF-κB pathway activity." (PMID 34350110, 2021). "Further, a recent study demonstrated the importance of MELK expression and its effects on the NF-κB pathway in melanoma proliferation." (PMID 33431809, 2021). "Previous studies have shown that multiple genes in melanoma cells, such as Wnt5a, MELK, and PTX3, can trigger the NFκB signaling pathway, thereby migrating and invading melanoma." (PMID 33679872, 2020). "MELK-KO melanoma and colorectal cancer clones grew at wild-type levels in vitro, demonstrating that MELK is dispensable for proliferation in these cancer types as well." (PMID 29417930, 2018). "MELK is also over-expressed in most types of solid tumors, including breast, colon, liver, lung, melanoma, and ovarian cancer." (PMID 28337968, 2017). "In addition, maternal embryonic leucine zipper kinase (MELK)-mediated melanoma growth by activating nuclear factor kappa B (NF-κB) pathway via sequestosome 1 (SQSTM1/p62) has been shown in BRAF-mutant melanoma cell lines." (PMID 41197182, 2025). "Dual targeting of AMPK/MELK is used for the treatment of novel melanoma." (PMID 38382096, 2024). "MELK is often highly expressed in melanoma patients' samples compared to normal skin tissue." (PMID 38382096, 2024). "Metabolic activity of melanoma cells and the potential overexpression of MELK in these cells seem to be important for CRO15-induced cell death and could explain why normal human or mouse cells are not affected by this compound." (PMID 33431809, 2021). "We then determined the consequences of MELK inhibition for melanoma cells." (PMID 33431809, 2021). "Thus, inhibition of MELK in combination with BRAF inhibitors allows for an effect on resistant melanoma cell viability compared to BRAF inhibitors alone and decreases the development of resistance." (PMID 33431809, 2021).